NOTCH1 (notch receptor 1)
Diseases named in the same sentence as NOTCH1 in open-access papers (continued):
Sharing a sentence is not in itself a finding about the gene and the disease.
pancreatic cancer (123 papers, 2009 to 2025). "Many studies found that Notch1 upregulation in different cancer types, including pancreatic cancer cells, was associated with lower survival rates." (PMID 38817387, 2024). "In the current study, we examined the anticancer role of umbelliprenin in pancreatic cancer and investigated its underlying mechanisms involving Akt/mTOR and Notch1 signaling pathways to regulate apoptosis, autophagy, and cancer cell stemness." (PMID 37409635, 2023). "PDGF-BB bound to PDGFR-β and caused interaction of Notch1 with Furin, encouraging cell invasion and metastasis in pancreatic cancer." (PMID 37865637, 2023). "Another experimental study reported the suppression of PanIN (Pancreatic Intraepithelial Neoplasias) caused by Notch-1 in a mouse model of pancreatic cancer." (PMID 35686109, 2022). "We performed independent evaluations of the impacts of Notch1 or Notch4 loss in the context of previously established GEMMs for pancreatic cancer, LSL-KrasG12D;p48-Cre and p16fl/fl;LSL-KrasG12D;p48-Cre GEMMs." (PMID 36970723, 2022). "Ectopic expression of miR-34a, as tumor suppressive miR, caused downregulation of Bcl-2, Notch1, and Notch2 and also inhibition of cell proliferation and invasion, induction of apoptosis and cell cycle arrest in pancreatic cancer cells." (PMID 32489562, 2020). "In murine models of pancreatic cancer, the deletion of Lnfg causes an increased expression of Notch1, Notch3 and Hes1, resulting in an accumulation of aldehyde dehydrogenase 1 (ALDH1)-positive undifferentiated progenitor cells." (PMID 32796631, 2020). "Our findings contribute to the elucidation of the mechanism underlying Notch1 functions in the progression of pancreatic cancer." (PMID 28145431, 2017). "The NOTCH1 germline variant that was present in one of our patients (patient 29), was also found in somatic variants in the TCGA PanCancer Atlas, in an individual affected with pancreatic cancer." (PMID 40627234, 2025). "For this, pancreatic cancer cells were transfected with plasmids encoding Notch-1." (PMID 30484491, 2018). "In some cancer types, NOTCH2 has shown a significant relevance to aggressiveness and carcinogenesis instead of NOTCH1, such as gastric cancer, hepatic carcinoma, pancreatic cancer, and bladder cancer." (PMID 40387567, 2025). "EOGT facilitates O-GlcNAcylation of NOTCH1 in pancreatic cancer, promoting the nuclear localization of the Notch intracellular domain (NICD) and this process contributes to the suppression of E-cadherin and P21 transcription, supporting PDAC progression." (PMID 40909272, 2025). "The STAT1, STAT3, EGFR, and Notch‐1 signaling pathways can be blocked to prevent the development of pancreatic cancer." (PMID 38690008, 2024). "Apoptotic death and inhibition of pancreatic cancer stem cells were unveiled by TQ via Notch1 and PI3K/Akt/mTOR-regulated autophagy signaling pathways." (PMID 38532470, 2024). "Curcumin has the ability to inhibit not only the protein phosphorylation of STAT1 and STAT3 but also the EGFR and Notch‐1 signaling processes, all of which play important roles in the progression of pancreatic cancer." (PMID 38690008, 2024). "The expression of Snail1 and Notch1 is regulated by MiR-34a, which inhibits the spread of pancreatic cancer." (PMID 38725047, 2024). "Studies have confirmed that APOL1 promotes the proliferation and invasion of pancreatic cancer cells by activating the NOTCH1 signaling pathway." (PMID 38410113, 2024). "This was evidenced by multiple studies showing increased NOTCH1 expression in pancreatic cancer cells." (PMID 38730578, 2024). "In this study, we investigated the effects of silencing NF-κB1, ANGPTL4 and Notch1 genes in combination with gemcitabine on the viability of pancreatic cancer cell line (PANC-1) in vitro." (PMID 38817387, 2024). "Second, the designed stapled peptide, SAH-mAH2-5, exhibited profound anti-pancreatic cancer effects, especially in Notch1-hyperactivated pancreatic cancer, in multiple preclinical models." (PMID 37714834, 2023).
pancreatic cancer (continued). "YEATS4 can bind to H2A.Z2, which in turn drives the activation of NOTCH1, upregulates the expression of NOTCH1 and its downstream mediator Hes1, and mediates the occurrence and drug resistance of pancreatic cancer." (PMID 37435030, 2023). "Taken together, these data suggest that SAH-mAH2-5, similar to N1DARP, suppresses pancreatic cancer initiation and progression by ameliorating the Notch1 pathway, with limited off-target and toxic effects." (PMID 37714834, 2023). "SAH-mAH2-5 injection provided substantial therapeutic benefits with limited off-target and systemic adverse effects in Notch1-activated pancreatic cancer models." (PMID 37714834, 2023). "Notch 1 was previously reported to be elevated in pancreatic cancer and represents a potential target in pancreatic cancer." (PMID 36685076, 2023). "Studies have shown that LFNG deficiency accelerates KRAS-induced pancreatic cancer development in mice, while LFNG expression inhibition suppresses pancreatic cancer cell proliferation and migration by inhibiting NOTCH1 activation." (PMID 37932706, 2023). "The activation of the Notch1 signalling cascade plays a pivotal role in the development of acquired resistance and gemcitabine-induced stemness in pancreatic cancer cells." (PMID 36685076, 2023). "NOTCH1 and oncogenic gene Ras synergistically facilitate the epithelial-mesenchymal transition in pancreatic cancer." (PMID 35897085, 2022). "A decrease in the activated Notch1 and PTEN protein levels can predict prognoses and chemotherapeutic resistance.GEM can induce the upregulation of Notch1 in pancreatic cancer cells and increase the expression of the Notch intracellular domain (NICD)." (PMID 36686732, 2022). "The GEN-mediated upregulation of miR-34a in pancreatic cancer cells also inhibited the Notch-1 signaling pathway, whose activation promotes cancer cell growth and metastasis." (PMID 35744941, 2022). "Sulforaphane inhibited Notch-1, and negated a gemcitabine-induced rise in Notch-1 expression in pancreatic cancer cells cultured in vitro." (PMID 35408894, 2022). "The retinoids 4-HPR, Cl-AHPC, and AHP3 inhibited Notch-1 in neuroblastoma and pancreatic cancer cell lines." (PMID 35408894, 2022). "Phenethyl isothiocyanate (PEITC), a cruciferous-vegetables-derived isothiocyanate, suppressed Notch-1 and Notch-2 levels, reduced cell proliferation, and induced apoptosis in pancreatic cancer cells." (PMID 35408894, 2022). "Notch1 inhibition induces increased the rate of apoptosis, migration, and intrusive properties of pancreatic cancer cells with γ-secretase inhibitors." (PMID 33670230, 2021). "In conclusion, our findings show that MSCs increased SNHG7 expression in pancreatic cancer cells, promoting the stemness and Folfirinox resistance via the Notch1/Jagged1/Hes-1 signaling pathway." (PMID 34631547, 2021). "Overexpression of Notch2 and Jagged1 has been shown in gemcitabine resistant pancreatic cancer cells, whereas Notch1 is a crucial downstream mediator of Kirsten rat sarcoma viral oncogene homology (KRAS), and control tumor sphere formation of pancreatic cells." (PMID 33670230, 2021). "In pancreatic cancer, Notch1 inhibits the expression of p21 and p27 by activating Cyclin D1 expression, and promotes tumor cell cycle." (PMID 33781318, 2021). "To determine the combined effect of CDK5 and Notch1 signaling on pancreatic cancer cells, we measured the effect of blocking CDK5 and/or Notch signaling on cell proliferation and migration." (PMID 33960694, 2021). "Using RT-qPCR, the three most substantially elevated mRNAs in pancreatic cancer cells in response to co-culture with MSCs were Notch1, FMR1, and U2AF2." (PMID 34631547, 2021). "The current findings indicate that STAT3 and CASP3 are related to liver cancer, while NOTCH1 and CTNNB1 are associated with pancreatic cancer." (PMID 35154607, 2021). "Oncogenic NOTCH1 pathway was activated by MACC1-AS1 through pyruvate kinase M2 in the pancreatic cancer cells." (PMID 34178644, 2021).
pancreatic cancer (continued). "Here, we used the inhibitors to explore the combined effect of CDK5 and Notch1 signaling on pancreatic cancer cells growth." (PMID 33960694, 2021). "Similar to what was described in pancreatic cancer, Midkine-mediated upregulation of Notch1, responsible for Notch2 upregulation, was also reported as a resistance mechanism for biliary tract cancer." (PMID 34680255, 2021). "Mechanistic investigations revealed that SNGH7 interacted with Notch1 to regulate the stemness and Folfirinox resistance through the Notch1/Jagged1/Hes-1 signaling pathway in pancreatic cancer." (PMID 34631547, 2021). "To further verify that USP18 regulates c-Myc expression through Notch1 in pancreatic cancer cells, we decreased the expression of Nothc1 in USP18-overexpressing pancreatic cancer cells and then observed the Nothc1 and c-Myc protein levels." (PMID 33051403, 2020). "Our results indicated that protein levels of Notch1 were significantly upregulated in pancreatic cancer tissues compared with corresponding adjacent normal tissues." (PMID 33051403, 2020). "Luciferase reporter assays revealed that in pancreatic cancer, miR-34a targets both SNAIL and NOTCH1 to inhibit pancreatic cancer progression through the regulation of EMT and NOTCH signaling pathways." (PMID 31947678, 2020). "Downregulation of miR-299-3p suppresses pancreatic cancer malignant progression through the blockade of the Notch1 pathway." (PMID 33425718, 2020). "Confocal microscopy was used to further confirm the co-localization of USP18 and Notch1 in pancreatic cancer cells, which provided further evidence of an interaction between these two proteins." (PMID 33051403, 2020). "Scatter plots revealed that USP18 and Notch1 protein expression levels were positively correlated in pancreatic cancer tissues." (PMID 33051403, 2020). "Overall, these results demonstrated that USP18 contributes to the progression of pancreatic cancer and is dependent on the Notch1/c-Myc signalling pathway." (PMID 33051403, 2020). "The results showed that the donwnregulation of Notch1 inhibited the increases in c-Myc expression observed in USP18-overexpressing pancreatic cancer cells." (PMID 33051403, 2020). "Previous studies demonstrated that the Notch1-c-Myc signalling pathway plays an important role in pancreatic cancer progression." (PMID 33051403, 2020). "The upregulation of Notch-1 in pancreatic cancer cells induces overexpression of miR-21 and underexpression of let-7a and let-7b." (PMID 32489562, 2020). "Notch1 signaling sustains the progression of some of the most aggressive human malignancies, including leukemia, pancreatic carcinomas, and GBM." (PMID 31752162, 2019). "On the contrary, transfection with HtrA1-specific siRNA significantly increased the Notch-1 transcripts in pancreatic cancer cells." (PMID 30484491, 2018). "We found that the suppressive function of HtrA1 on cell proliferation was abolished upon up-regulation of Notch-1 in pancreatic cancer cells." (PMID 30484491, 2018). "In contrast, HtrA1-specific siRNA knockdown enhanced the expression levels of Notch-1 in pancreatic cancer cells." (PMID 30484491, 2018). "It has been suggested that aberrant activation of Notch1 helps cells acquire epithelial–mesenchymal transition and CSC self-renewal properties and is associated with pancreatic cancer treatment failure." (PMID 30486896, 2018). "In conclusion, the present study showed that HtrA1 inhibited the proliferation of pancreatic cancer cells by modulating Notch-1 expression." (PMID 30484491, 2018). "Collectively, our findings revealed that HtrA1 played a critical role in the proliferation of pancreatic cancer cells mediated by Notch-1." (PMID 30484491, 2018). "Together, our results suggest that low-dose gemcitabine treatment activates Notch1 signaling and induces stemness in pancreatic cancer cells." (PMID 30486896, 2018).
pancreatic cancer (continued). "A mouse xenograft model of pancreatic cancer was established to determine the effect of Notch1 inhibition on the killing effect of gemcitabine in vivo." (PMID 30486896, 2018). "In this study, we verified that the hypoxic niche synergistically enhances gemcitabine-induced stemness and acquired resistance in pancreatic cancer cells by activating the AKT/Notch1 signaling cascade." (PMID 30486896, 2018). "Our results showed that gemcitabine treatment increased the migratory and invasive abilities of pancreatic cancer cells, whereas suppression of Notch1 significantly abolished these increases." (PMID 30486896, 2018). "To further confirm the role of Notch1 in gemcitabine-enhanced stemness, we pretreated pancreatic cancer cells with 10 μM γ-secretase inhibitor DAPT for 24 h before gemcitabine treatment." (PMID 30486896, 2018). "Accumulating studies have reported the dysregulated expression of Notch-1 in several cancers, including pancreatic cancer." (PMID 30484491, 2018). "In the current research, we found that enforced expression of HtrA1 suppressed Notch-1 expression in pancreatic cancer cells." (PMID 30484491, 2018). "In pancreatic cancer, miR-34a inhibits Notch1-induced cell cycle arrest and decreases cell invasion." (PMID 29190930, 2017). "A correlation between E-cadherin and Notch-1 has been reported in trophoblast cells and pancreatic cancer cells." (PMID 28356132, 2017). "In vivo, we also demonstrated that miR-34a inhibited pancreatic cancer growth by decreasing Snail1 and Notch1 expression." (PMID 28145431, 2017). "We altered the Snail1 or Notch1 gene expression levels in pancreatic cancer cell lines by transfection with gene expression vectors or shRNAs for 24 h." (PMID 28145431, 2017). "Because the EMT program activator Snail1 and the proliferation regulator Notch1 are both targets of miR-34a, miR-34a is vital to the progression of pancreatic cancer." (PMID 28145431, 2017). "In our study, we showed that miR-34a and Notch1 repress the expression of each other and constitute a positive feedback loop in pancreatic cancer cells." (PMID 28145431, 2017). "Overexpression of Notch1 downregulated miR-34a expression levels in pancreatic cancer, and the downregulation of miR-34a alleviated its inhibition of the Notch1 gene, resulting in increased Notch1 protein expression." (PMID 28145431, 2017). "In AsPC-1 pancreatic cancer cells, Notch-1 overexpression affected the expression of miRNAs: overexpression of Notch-1 led to increased expression of miR-21 and decreased expression of miR-200b." (PMID 27231938, 2016). "The cancer development of organs has been regulated by Notch-1 signaling, which directly promotes Snail, Slug and NF-κB in BxPC-3 human pancreatic cancer cell." (PMID 27231938, 2016). "In vitro studies, applying a COX-2-selective inhibitor to COX-2-positive pancreatic cancer cells, revealed that expression of Notch1, Hes1 and DLL1 depended on COX-2-mediated prostaglandin synthesis." (PMID 27381829, 2016). "More importantly, miR-223 governs GR-induced EMT in part due to down-regulation of its target Fbw7 and subsequent upregulation of Notch-1 in pancreatic cancer." (PMID 25638153, 2015). "We previously reported that exosomes secreted by human pancreatic tumor cells induce cell death through the inhibition of the Notch-1 survival pathway." (PMID 25821841, 2015). "Consistent with the recent observation that SFK inhibition was able to decrease the active cleaved form of NOTCH1 in pancreatic cancer cells, we found that SI221 greatly decreased the cleaved form of NOTCH3 in both RD and RH30 cell lines." (PMID 25762618, 2015). "Recent data implicated SFKs in the NOTCH pathway, showing that SFK inhibition decreased the active cleaved form of NOTCH1 in pancreatic cancer cells." (PMID 25762618, 2015). "Another novel study indicated that miRNA-34 also had an impact on stemness of pancreatic cancer cells potentially by targeting Bcl-2 and Notch1/2." (PMID 24587996, 2014).
pancreatic cancer (continued). "In pancreatic cancer cell lines, the activation of Notch1 signaling has been found to contribute to invasion and metastasis by EMT." (PMID 24932308, 2014). "Upregulation of Notch-1 is implicated in inducing epithelial-mesenchymal transition (EMT), which has been previously reported to increase the invasive properties of pancreatic cancer cells." (PMID 24391839, 2013). "In pancreatic cancer cells, pulse of NOTCH1 activation led to increased expression of NOTCH target genes namely HES1 and c-MYC." (PMID 24392017, 2013). "Co-localization of Notch-1 and c-Src was confirmed in xenograft tumor tissues and in the tissues of pancreatic cancer patients." (PMID 22479394, 2012). "In the present study, we found that overexpression of Notch-1 increases colony formation of HPAC pancreatic cancer cells." (PMID 22479394, 2012). "We have previously observed that over-expression of the Notch-1 intracellular domain (NICD) increases pancreatic cancer cell growth, and knocking down Notch-1 inhibits cell growth." (PMID 22479394, 2012). "Down-regulation of Notch-1 contributes to cell growth inhibition and apoptosis in pancreatic cancer cells, including BxPC-3, HPAC, and PANC-1." (PMID 23071601, 2012). "We previously reported that exosomes secreted by human SOJ-6 pancreatic tumor cells induce (glyco)protein ligand-independent cell death and inhibit Notch-1 pathway, this latter being particularly active during carcinogenesis and in cancer stem cells." (PMID 23094054, 2012). "3-Cl-AHPC-induced apoptosis was preceded by decreasing expression of IGF-1R, cyclin D1, β-catenin, and activated Notch-1 in the pancreatic cancer cell lines." (PMID 22570653, 2012). "The interaction of these exosomes with pancreatic cancer cells also led to decreased expression of the intranuclear target of the Notch-1 signaling pathway, thereby inhibiting the Notch-1 survival pathway and activating the apoptotic pathway." (PMID 22190973, 2011). "Using a pancreas cancer tissue microarray, we noted that Jagged1, Notch3 and Notch4 are overexpressed in pancreas tumors (26%, 84% and 31% respectively), whereas Notch1 is expressed in blood vessels." (PMID 22074495, 2011). "In an in vitro setup, we have also demonstrated that stemness-like state can be achieved in the presence of Cyr61 through the regulation of multiple stemness traits including ABCG2, Notch-1, Oct-4 and CD-44 in pancreatic cancer cells." (PMID 21232118, 2011). "It has been demonstrated that APOL1 may function as an oncogene to stimulate proliferation and block apoptosis by triggering the expression of the NOTCH1 signaling pathway in pancreatic cancer." (PMID 39091293, 2024). "NOTCH1 stimulates cell invasion and metastasis in pancreatic cancer cells." (PMID 38730578, 2024). "Notch1 shRNA decreased MiR-34a’s anti-apoptotic effects on pancreatic cancer cells." (PMID 38725047, 2024). "MiR-34a inhibited pancreatic cancer growth in vivo by reducing the expression of Snail1 and Notch1." (PMID 38725047, 2024). "The NOTCH1 gene is another gene that plays an oncogenic role in pancreatic cancer." (PMID 38730578, 2024). "Based on these facts, MACC-AS1/PAX8/Notch1 signalling might be considered as a target for the alternative treatment of pancreatic carcinoma patients." (PMID 37628760, 2023). "MSCs could increase the expression of SNHG7 in pancreatic cancer cells, which would promote the dryness and Folfirinox resistance of pancreatic cancer cells through the Notch1/Jagged1/Hes-1 signaling pathway." (PMID 35281017, 2022). "Likewise, hypoxia‐induced AKT activation contributes to gemcitabine‐induced stemness of pancreatic cancer cells by enhancing downstream Notch1 activity." (PMID 36226253, 2022). "Moreover, a natural compound, genistein, inhibited cell growth and induced apoptosis in pancreatic cancer cells through the upregulation of miR-34a, leading to decreased Notch1." (PMID 35887021, 2022).